BUB1 (BUB1 mitotic checkpoint serine/threonine kinase)
Diseases named in the same sentence as BUB1 in open-access papers (continued):
Sharing a sentence is not in itself a finding about the gene and the disease.
neuroblastoma (3 papers, 2022 to 2023). Neuroblastoma (NB) is the most common solid, extracranial childhood tumor. "Further regression analyses suggested that bub1 expression was a risk factor irrelevant to MYCN amplification for the poor survival of neuroblastoma patients, supporting its role as an independent prognostic biomarker." (PMID 36237324, 2022). "High bub1 expression was found to be associated with clinicopathological development of neuroblastoma in children." (PMID 36237324, 2022). "Owing to it association with MYCN, it is reasonable to speculate that bub1 is also involved in the development of neuroblastoma and may be used to guide targeted immunotherapy against neuroblastoma." (PMID 36237324, 2022). "In both groups, patients with high bub1 expression showed lower overall survival rates than those with low bub1 expression (p = 0.032, p = 0.083), further supporting the role of bub1 as an independent prognostic biomarker for neuroblastoma." (PMID 36237324, 2022). "Correlation between bub1 expression levels and demographic/clinicopathological factors of neuroblastoma." (PMID 36237324, 2022). "This study aimed to clarify the role of bub1 in the pathogenicity of neuroblastoma and as a prognostic biomarker for neuroblastoma." (PMID 36237324, 2022). "In order to gain more insight into the biological functions of bub1, we silenced bub1 in two neuroblastoma cell lines SH-SY5Y and SK-N-SH." (PMID 36237324, 2022). "Using bioinformatics, molecular biological tools, and public datasets, we successfully identified a new oncogene bub1 in neuroblastoma patients." (PMID 36237324, 2022). "A future in-depth study using our patient data will deepen our understanding of the role of bub1 in the pathogenesis and prognosis of neuroblastoma." (PMID 36237324, 2022). "We employed TARGET neuroblastoma RNA-Seq data to study the relationship between bub1 expression and host immune infiltration." (PMID 36237324, 2022). "Our study of pediatric neuroblastoma found that silencing bub1 led to increased expression of GSK3β and p-GSK3β and suppressed expression of p-GSK3β/GSK3β." (PMID 36237324, 2022). "Using bioinformatics and molecular biological tools, we identified bub1, a tumor-related gene in neuroblastoma." (PMID 36237324, 2022). "In order to verify the interference efficiency of bub1 siRNA in neuroblastoma cells, we transfected two bub1-specific siRNA into SH-SY5Y and SK-N-SH cells respectively." (PMID 36237324, 2022). "Expression of bub1 was found to significantly affect overall survival and event-free survival of patients with neuroblastoma, positively correlate with the expressions of tpx2 and the ASPM gene, and negatively correlate with host immune infiltration." (PMID 36237324, 2022). "Synthetic small interfering RNAs (siRNAs) were employed to silence bub1 expression in neuroblastoma cell lines SH-SY5Y and SK-N-SH, in order to characterize its biological functions." (PMID 36237324, 2022). "Another limitation was that no direct experimental evidence has been provided to support the role of bub1 in neuroblastoma immune infiltration." (PMID 36237324, 2022). "Using gene enrichment analysis, the top 25 genes most relevant to bub1 in neuroblastoma were presented as heat maps." (PMID 36237324, 2022). "Colony formation assays further suggested reduced proliferation of si-bub1 neuroblastoma cells relative to its si-NC counterparts." (PMID 36237324, 2022). "Expression of bub1 was elevated in patients with neuroblastoma in the TARGET dataset." (PMID 36237324, 2022). "This study evaluated bub1 as an oncogene and a prognostic biomarker for neuroblastoma." (PMID 36237324, 2022). "Expression of bub1 was elevated in patients with neuroblastoma." (PMID 36237324, 2022). "It was noticed that bub1 affected the proliferation and migration of neuroblastoma cells." (PMID 36237324, 2022).
neuroblastoma (continued). "Results from three data sets all suggested that patients with high bub1 expression had lower overall survival rates and recurrence-free survival rates than those with low bub1 expression, implicating a potential role of bub1 as a prognostic biomarker for patients with neuroblastoma." (PMID 36237324, 2022). "We identified a potential tumor-promoting gene bub1 for neuroblastoma that could also serve as a prognostic biomarker." (PMID 36237324, 2022). "High expression of bub1 in neuroblastoma thus may predict poor prognosis of the patient." (PMID 36237324, 2022). "In addition to apoptosis, EMT, and Wnt signaling pathway, other mechanisms driven by bub1 expression and underpinning the development of neuroblastoma may also exist." (PMID 36237324, 2022). "To further clarify whether bub1 expression was simply a coeffect of other risk factors such as MYCN amplification in predicting neuroblastoma survival, we divided patients into groups with or without MYCN amplification." (PMID 36237324, 2022). "To assess the functional requirement of mitotic genes in established neuroblastoma, we next quantified the effect of silencing two representative genes within the MSG in neuroblastoma cell lines, BUB1 and KIFC1." (PMID 37958555, 2023). "To investigate the effect of MYCN on mitotic dysregulation and its functional consequences in neuroblastoma cells, we performed siRNA knockdown of AURKB, BUB1, and KIFC1 in MYCN-regulable SHEP21N cells." (PMID 37958555, 2023). "The expression of bub1 significantly affected the expression of proteins involved in epithelial-mesenchymal transition (EMT), cell apoptosis, and the Wnt signaling pathway, three biological underpinnings of the pathogenesis of neuroblastoma." (PMID 36237324, 2022). "To determine whether AURKB, BUB1, and KIF1C are MYCN target genes, we performed ChIP-PCR and demonstrated a 4-to-10-fold enrichment of MYCN binding to the promoter regions in two MYCN-amplified neuroblastoma cell lines." (PMID 37958555, 2023).
adenoma (2 papers, 2020). A neoplasm arising from the epithelium. "Comparing of corresponding adenomas, the expressions of BUB1, BUB1B, PLK4, and DNA2 in carcinomas were higher." (PMID 33134313, 2020).
brain tumor (2 papers, 2020 to 2024). "In brain tumours (GBM and LGG), BUB1 expression was elevated in the G-CIMP low subtype." (PMID 38396175, 2024).
dengue (2 papers, 2023 to 2025). "While several genes consistently identified dysregulated in dengue patients, such as CXCL10, ZWINT, BUB1, AURKA, STAT1, etc. there was a notable variability in gene expression patterns across the datasets." (PMID 40100920, 2025). "The GO analysis revealed that the genes BUB1, RRM2, IFI27, DLGAP5, and CEP55 exhibit 4-fold up-regulation in dengue and SD patients however, they exhibit downregulation in CP." (PMID 38076406, 2023). "Key regulatory genes such as AURKA, BUB1, BUB3, and CDK1 are found to be involved in cell cycle regulation and have roles in immune-related pathways, underscoring their importance in the host immune response to Dengue virus infection." (PMID 40100920, 2025).
developmental delay (2 papers, 2021 to 2022). "A copy number loss encompassing a similar interval (including MALL, NPHP1, LIMS3, RGPD6, and BUB1) has been reported in ClinVar as a variant of uncertain significance with the phenotype of developmental delay and facial dysmorphisms (SCV000709783.2)." (PMID 33597717, 2021).
leiomyosarcoma (2 papers, 2021 to 2025). An uncommon, aggressive malignant smooth muscle neoplasm, usually occurring in post-menopausal women. "All this evidence allows us to propose BUB1 as a key kinase in the progression of OS, liposarcoma, leiomyosarcoma, and synovial sarcoma." (PMID 40723917, 2025). "In the Barretina Sarcoma dataset, BUB1 was upregulated in myxofibrosarcoma, pleomorphic liposarcoma, and leiomyosarcoma with 3.085 (P = 6.53E-14), 2.926 (P = 1.22E-09), and 2.878 (P = 5.95E-09) fold changes, respectively." (PMID 33872216, 2021).
mesothelioma (2 papers, 2012 to 2025). A usually malignant and aggressive neoplasm of the mesothelium which is often associated with exposure to asbestos. "Thus, BUB1 levels were elevated in MPM tumors and other mesothelioma tissues (MM)." (PMID 40180891, 2025). "BUB1 is also a possible negative prognostic factor in mesothelioma." (PMID 22905093, 2012).
microcephaly (2 papers, 2022 to 2023). A congenital or acquired developmental disorder in which the circumference of the head is smaller than normal for the person's age and sex. "Here, we describe the first two patients with biallelic BUB1 germline mutations, who both display microcephaly, intellectual disability, and several patient-specific features." (PMID 35044816, 2022).
papillary renal cell carcinoma (2 papers, 2019 to 2022). A rare subtype of renal cell carcinoma, arising from the renal tubular epithelium and showing a papillary growth pattern, which typically manifests with hematuria, flank pain, palpable abdominal mass or nonspecific symptoms, such as fatigue, weight loss or fever. "In general, the 5-mRNA (CCNB2, IGF2BP3, KIF18A, PTTG1, and BUB1) were identified and validated, which can predict papillary renal cell carcinoma patient survival." (PMID 30822312, 2019). "We identified 5 mRNAs that are associated with the survival of patients with papillary renal cell carcinoma,namely CCNB2, IGF2BP3, KIF18A, PTTG1, and BUB1 in the training set." (PMID 30822312, 2019). "Interestingly, these KNL1-related molecules (e.g., BUB1, ASPM, TOP2A) have been implicated in immune infiltration in papillary renal cell carcinoma in another report." (PMID 36685823, 2022).
papillary thyroid cancer (2 papers, 2024 to 2025). "Knockdown of BUB1 attenuated cell viability, invasion, migration and induced cell cycle arrests, whereas overexpression of BUB1 promoted the cell cycle progression of papillary thyroid cancer cells." (PMID 38498903, 2024).
psoriasis (2 papers, 2023 to 2025). An autoimmune condition characterized by red, well-delineated plaques with silvery scales that are usually on the extensor surfaces and scalp. "In a previous transcriptomic analysis of mild and severe plaque psoriasis, BUB1 has been identified as one of the central hub genes in severe psoriasis." (PMID 40560938, 2025).
viral infection (2 papers, 2018). "Bub1 deficiency empowers the host to have the ability to resist viral infection in Drosophila and a human cell line." (PMID 29976667, 2018). "Thus, it needs to be further determined whether reduced TGFβ signaling activity in bub1-deficient flies contributes to resistance to viral infection as well, through strengthening innate immune responses." (PMID 29976667, 2018). "Here, we found that Bub1 has a novel function in the cytoplasm to assist virus infection by regulating endocytosis." (PMID 29976667, 2018). "This warranted further investigation into whether Bub1 could potentiate and stabilize endocytic complex formation in response to viral infection." (PMID 29976667, 2018). "It will be interesting to test if the BUB1 kinase activity is required for vesicle trafficking and, if so, BUB1 may be a viable target for limiting viral infections." (PMID 30555826, 2018). "Interestingly, coimmunoprecipitation assays indicated that the DCV capsid protein might interact with Bub1, and virus infection promoted more Bub1 protein to translocate onto the cell membrane and gather as large puncta." (PMID 29976667, 2018).
abortion (1 paper, 2012). the ending of pregnancy by removing a fetus or embryo before it can survive outside the uterus. "In our previous study, spontaneous abortion embryos contained low level of Bub1 protein but normal mRNA expression, indicating that the Bub1 expression may be regulated at post-transcriptional level." (PMID 23110129, 2012).
Alzheimer’ s disease (1 paper, 2024). "BUB1 was found to be highly expressed in the brain tissue of Alzheimer’ s disease (AD) patients and is a promising gene signature for diagnosis and therapy of AD." (PMID 39684322, 2024).
aneuploidy (1 paper, 2025). Chromosomal disorder consisting of the presence a chromosomal abnormality in which there is an addition or loss of chromosomes within a set. "This study aimed to evaluate the probable roles of BUB1 and BUBR1 pathogenic variants in abortion of the fetuses with aneuploidy." (PMID 40028477, 2025).
cholangiocarcinoma (1 paper, 2023). A carcinoma that arises from the intrahepatic biliary tree (intrahepatic cholangiocarcinoma) or from the junction, or adjacent to the junction, of the right and left hepatic ducts (hilar cholangiocarcinoma). "BUB1 and BUB1B may accelerate the process of cholangiocarcinoma by promoting the mitosis of cholangiocytes." (PMID 36979826, 2023).
chronic lymphocytic leukemia (1 paper, 2019). "To better investigate this assumption, we evaluated CIN associated with the miR-155/BUB1 axis at the late passages of our HDF immortalized models and in a cohort of patients with chronic lymphocytic leukemia." (PMID 31018621, 2019). "Here we show that the heterogeneous nuclear ribonucleoprotein L (HNRNPL) binds to the polymorphic marker D2S1888 at the 3′UTR of BUB1 gene, impairs the miR-155 targeting, and restores BUB1 expression in chronic lymphocytic leukemia." (PMID 31018621, 2019).
colorectal adenocarcinoma (1 paper, 2021). The most common type of colorectal carcinoma. "MAD2L1 and BUB1 are critical components of the spindle assembly and are known to be important drivers of carcinogenesis in colorectal adenocarcinoma." (PMID 34070979, 2021).
COVID-19 (1 paper, 2023). A disease caused by infection with severe acute respiratory syndrome coronavirus 2. "A few studies have demonstrated that BUB1 critically influences the pathophysiological processes of COVID-19." (PMID 37278873, 2023). "In our study, BUB1 negatively correlated with COVID-19 and silicosis, indicating a better prognosis." (PMID 37278873, 2023). "In our study, seven genes (BUB1, PRC1, KIFC1, RRM2, CDKN3, CCNB2, and MCM6) were involved in the interaction between COVID-19 and silicosis." (PMID 37278873, 2023). "Finally, submodule analysis showed that PRC1, KIFC1, BUB1, MCM6, CCNB2, CDKN3, and RRM2, which were hub-shared genes of silicosis and COVID-19, possessed the highest mCODE scores." (PMID 37278873, 2023).
gastric tumors (1 paper, 2023). "Additionally, BUB1/3 are simultaneously overexpressed in gastric tumors and exhibit a significant correlation with Ki-67 expression." (PMID 36787437, 2023).
intrahepatic cholangiocarcinoma (1 paper, 2025). A carcinoma that arises from the intrahepatic bile duct epithelium in any site of the intrahepatic biliary tree. "Moreover, BUB1 is a potential biomarker for predicting outcomes in liver intrahepatic cholangiocarcinoma and gauging the condition’s immune profile." (PMID 40236649, 2025).
lactic acidosis (1 paper, 2013). Metabolic acidosis characterized by the accumulation of lactate in the body. "Since hyperactivated mitotic checkpoint is another major mechanism that leads to human tumor CIN, we tested if glucose deprivation with lactic acidosis could disturb the expression of the mitotic checkpoint genes such as mad2, bub1, bub3, and bub1b." (PMID 23675453, 2013).
malignant mesothelioma (1 paper, 2025). A malignant neoplasm of the pleura or peritoneum, arising from mesothelial cells. "To strengthen these findings, we then conducted IHC profiling of BUB1 expression in a human tissue microarray (TMA) with 10 MPM cases, 17 malignant mesothelioma of other tissues, and 10 normal tissues." (PMID 40180891, 2025).
metastatic melanoma (1 paper, 2008). A melanoma that has spread from its primary site to another anatomic site. "In contrast, the metastatic melanomas express higher levels of genes such as MAGE, GPR19, BCL2A1, MMP14, SOX5, BUB1, RGS20, and more." (PMID 18442402, 2008).
Miscarriage (1 paper, 2012). A pregnancy that ends at a stage in which the fetus is incapable of surviving on its own, defined as the spontaneous loss of a fetus before the 22th week of pregnancy. "We previously found that the decreased expression of Bub1 proteins is associated with spontaneous miscarriages." (PMID 23110129, 2012). "Our findings strongly suggest that miRNA-mediated targeting of Bub1 expression by miRNA may be implicated in the pathogenesis of spontaneous miscarriage." (PMID 23110129, 2012). "Our results strongly suggest that an abnormally decreased Bub1 level regulated by miRNAs may be implicated in the pathogenesis of spontaneous miscarriage." (PMID 23110129, 2012).
ovarian serous carcinoma (1 paper, 2017). "For example, BUB1 mRNA was significantly co-expressed with AURKB mRNA in advanced-stage ovarian serous carcinoma." (PMID 28427189, 2017).
ovarian tumor (1 paper, 2013). "We report three genes (IRAK1, CHEK1 and BUB1) to be significant in ovarian tumor samples for the first time, to the best of our knowledge." (PMID 23383610, 2013).
polyposis (1 paper, 2018). "We performed a mutational analysis of BUB1 and BUB3 in 456 uncharacterized mismatch repair-proficient hereditary non-polyposis CRC families and 88 polyposis cases." (PMID 29448935, 2018).
renal cell carcinoma (1 paper, 2021). "A previous study found that 10 cell proliferation genes, including BUB1, CCNB2, and CDK1, could act as indicators for response to immune checkpoint inhibitors in PD-L1 negative renal cell carcinoma." (PMID 34440557, 2021).
silicosis (1 paper, 2023). Silicosis is a respiratory disease caused by breathing in (inhaling) silica dust. "In the rat model exposed to silica inhalation for 4 weeks, Bub1, Kifc1, Mcm6, and Prc1 were upregulated in the silicosis group, while Cdkn3 was downregulated." (PMID 37278873, 2023).
soft tissue sarcoma (1 paper, 2025). A malignant neoplasm arising from muscle tissue, adipose tissue, blood vessels, fibrous tissue, or other supportive tissues excluding the bones. "Targeted inhibition of BUB1 may provide a novel strategy to reduce tumor growth and improve outcomes for patients with bone and soft tissue sarcomas." (PMID 40723917, 2025).
thyroid cancer (1 paper, 2023). "According to multivariate Cox regression analysis, BUB1 was an independent risk factor for thyroid cancer (HR: 4.21965, 95% CI: 2.10531-8.45738, P=0.00005)." (PMID 37745716, 2023). "K-M survival analysis and subsequent multiple logistic regression revealed that the expression of BUB1 and GINS2 were potential risk factors for disease-free survival (DFS) of thyroid cancer." (PMID 37745716, 2023). "Compared with normal thyroid tissue, 7 CRGs were more highly expressed in thyroid cancer, namely BUB1 (P<0.001), RPL3 (P<0.001), TTK (P<0.001), GINS2 (P<0.001), SLC26A6 (P<0.001), CDKN2A (P<0.001) and ZNHIT2 (P<0.001)." (PMID 37745716, 2023). "This means that BUB1 could be an independent prognostic factor for thyroid cancer." (PMID 37745716, 2023). "The three-gene model (FDX1, BUB1, RPL3) was constructed to predict DFS of 1, 3 and 5 years in thyroid cancer (AUC: 0.789, 0.733, 0.757)." (PMID 37745716, 2023). "Three CRG models (FDX1, BUB1, RPL3) could better predict the prognosis of thyroid cancer." (PMID 37745716, 2023).
toxoplasmosis (1 paper, 2025). A parasitic disease contracted by the ingestion or fetal transmission of toxoplasma gondii. "Virtual screeningof apicomplexan kinase inhibitors confirms stronger binding affinityfor TgCDPK1 over BUB1, supporting the continued development of selectivetherapeutics against toxoplasmosis." (PMID 40584317, 2025).
urothelial carcinoma (1 paper, 2020). A malignant neoplasm derived from the transitional epithelium of the urinary tract (urinary bladder, ureter, urethra, or renal pelvis). "By contrast, urothelial carcinomas subtypes with a poor prognosis display high expression of late cell cycle genes, including CDK1/cyclin B complex and its activators such as CDC25 family genes, and genes related to chromosome segregation and cell division such as BUB1, CDC20, and CENP." (PMID 31709755, 2020).